OR2A1 (olfactory receptor family 2 subfamily A member 1)
Description:
Odorant receptor.
Gene: Protein-coding gene on chromosome 7 (144,312,419 to 144,322,737, forward strand). Ensembl gene ENSG00000221970.
Subcellular location: Cell membrane
Pathways (Reactome):
Sensory Perception: Expression and translocation of olfactory receptors; Olfactory Signaling Pathway
Gene Ontology:
Molecular function: olfactory receptor activity; G protein-coupled receptor activity
Biological process: detection of chemical stimulus involved in sensory perception of smell; G protein-coupled receptor signaling pathway
Cellular component: plasma membrane; membrane
Genetic constraint (gnomAD): Missense variants: 0 observed, 22.59 expected, observed/expected ratio (o/e) 0, 90% interval 0 to 0.13. Synonymous variants: 1 observed, 7.94 expected, observed/expected ratio (o/e) 0.13, 90% interval 0.044 to 0.6.
Homologues: Orthologues: macaque OR2A1 (91% identical), dog OR2A9 (84% identical), dog OR2A9B (83% identical), mouse Or2a20 (80% identical), rat Or2a20 (79% identical), mouse Or2a57 (78% identical), rat Or2a57 (78% identical), mouse Or2a51 (78% identical), rat Or2a51 (76% identical). Paralogues in human: OR2A42 (100% identical), OR2A5 (80% identical), OR2A25 (73% identical), OR2A14 (73% identical), OR2A7 (71% identical), OR2A4 (70% identical), OR2A12 (69% identical), OR2A2 (66% identical), OR7C2 (46% identical), OR7C1 (45% identical), OR1C1 (45% identical), OR7A10 (45% identical), and 116 more.
Diseases named in the same sentence as OR2A1 in open-access papers:
OR2A1 is named in the same sentence as 2 diseases in open-access papers, as found by Europe PMC text mining. Sharing a sentence is not in itself a finding about the gene and the disease. The quoted sentences say what the papers report.
ovarian carcinoma (2 papers, 2013 to 2017). A malignant neoplasm originating from the surface ovarian epithelium. "These include four loci that were associated (unadjusted P<0.05) with breast cancer (GTF2H2, ZNF385B, NAALADL2 and PSG5), and two loci associated with ovarian cancer (CYP2A7 and OR2A1)." (PMID 28145423, 2017). "Eight of these 29 (28%) CNV loci were confirmed by qPCR and/or Nanostring analysis, including four loci that were associated with breast cancer (GTF2H2, ZNF385B, NAALADL2 and PSG5) and two loci that were associated with ovarian cancer (CYP2A7 and OR2A1)." (PMID 28145423, 2017). "The expression of OR2A1 is known to be regulated in response to chemotherapy in ovarian cancer." (PMID 23405139, 2013).
OR2A1 also shares sentences with these, for which no sentence is quoted: breast carcinoma (1 paper).